CRISP2 (cysteine rich secretory protein 2)
Description:
May regulate some ion channels' activity and thereby regulate calcium fluxes during sperm capacitation.
Synonyms: CRISP-2; CT36; GAPDL5; TPX1; TSP1
Tractability: Antibody: UniProt places it where antibodies can reach, with high confidence; UniProt predicts a signal peptide or a membrane-spanning region; its Gene Ontology location is reachable by antibodies, with medium confidence.
Gene: Protein-coding gene on chromosome 6 (49,692,358 to 49,714,703, reverse strand). Ensembl gene ENSG00000124490.
Subcellular location: Secreted
Gene Ontology:
Cellular component: extracellular region
Genetic constraint (gnomAD): Loss-of-function variants: 18 observed, 24.59 expected, observed/expected ratio (o/e) 0.73, 90% interval 0.5 to 1.09. The upper end of that interval is the gene's LOEUF score, 1.09, which puts it in group 4 of 6, group 1 being the genes least tolerant of losing a copy. Missense variants: 231 observed, 210.87 expected, observed/expected ratio (o/e) 1.1, 90% interval 0.98 to 1.22. Synonymous variants: 75 observed, 76.64 expected, observed/expected ratio (o/e) 0.98, 90% interval 0.81 to 1.19.
Homologues: Orthologues: chimpanzee CRISP2 (99% identical), rabbit CRISP2 (84% identical), pig CRISP2 (81% identical), guinea pig CRISP2 (79% identical), mouse Crisp2 (70% identical), rat Crisp2 (68% identical), tropical clawed frog crisp2l (33% identical), Caenorhabditis elegans scl-13 (28% identical), Caenorhabditis elegans scl-12 (28% identical), Caenorhabditis elegans scl-1 (26% identical), Caenorhabditis elegans scl-5 (26% identical), Caenorhabditis elegans scl-14 (26% identical), and 39 more. Paralogues in human: CRISP3 (72% identical), CRISP1 (44% identical), CRISPLD2 (32% identical), CRISPLD1 (31% identical), CLEC18B (30% identical), CLEC18A (30% identical), CLEC18C (30% identical), GLIPR1 (29% identical), GLIPR1L1 (27% identical), GLIPR1L2 (26% identical), PI15 (25% identical), R3HDML (23% identical), and 1 more.
Diseases named in the same sentence as CRISP2 in open-access papers:
CRISP2 is named in the same sentence as 27 diseases in open-access papers, as found by Europe PMC text mining. Sharing a sentence is not in itself a finding about the gene and the disease. The quoted sentences say what the papers report.
male infertility (8 papers, 2015 to 2024). The inability of the male to effect fertilization of an ovum after a specified period of unprotected intercourse. "An aberrant expression of CRISP2 is associated with male infertility due to its participation in gamete fusion; however, to our knowledge, there are no studies on CRISP (CRISP2 and CRISP3) expression in the semen of felid-related species." (PMID 38612267, 2024). "It is known that a decrease in CRISP2 content in sperm is associated with male infertility in humans and horses." (PMID 35327169, 2022). "This, therefore, suggest that there is an association between the level of CRISP2 expression and male infertility." (PMID 35173218, 2022). "The human CRISP2 gene is reported to occur at a location associated with translocations and male infertility." (PMID 25890347, 2015). "A decrease in CRISP2 amounts in the sperm is associated with male infertility." (PMID 37834239, 2023). "A decrease in CRISP2 amount in sperm is associated with male infertility." (PMID 36012418, 2022). "Decreased CRISP2 protein level in sperm was associated with human male infertility." (PMID 33996980, 2021). "CRISP2 genetic defects in sperm from humans and mice result in male infertility." (PMID 37705744, 2023).
asthenozoospermia (7 papers, 2019 to 2025). "In the context of differentially expressed (DE)-genes related to asthenozoospermia, special attention has recently been focused on Cysteine-Rich Secretory Protein 2 (CRISP2), Cation Channel Sperm Associated 1 (CATSPER1) and Prostate and Testis Expressed 1 (PATE1)." (PMID 34440724, 2021). "miRNAs also regulate motility: CRISP2 is key in sperm motility and acrosome reaction; miR-27a suppresses CRISP2, reducing motility in asthenozoospermia." (PMID 41356904, 2025). "A study assessed the expression of CRISP2 in the spermatozoa and seminal plasma fluid of three groups of infertile men (asthenozoospermia, teratozoospermia, and teratoasthenozoospermia), and then compared with the control (normozoospermic infertile men)." (PMID 35173218, 2022). "CRISP2 is also involved in sperm motility and spermiogenesis and has previously been shown to be significantly decreased in the seminal plasma of men with asthenozoospermia, teratozoospermia, and asthenoteratozoospermia." (PMID 38654926, 2024). "Reduced CRISP2 protein levels were found in azoospermia and asthenozoospermia." (PMID 34041237, 2021). "The purpose of this study was to analyze the expression level of CRISP2, CATSPER1, PATE1 and SEMG1 genes in the sperm of men with asthenozoospermia (AZS)." (PMID 31058050, 2019).
atherosclerosis (6 papers, 2017 to 2025). A disease characterized by the build-up of fatty material and calcium deposition in the arterial wall resulting in partial or complete occlusion of the arterial lumen. "DMRs in the promoter region of BRCA1 and CRISP2 were consistently associated with subclinical atherosclerosis measures, suggesting their potential blood surrogate markers for early risk stratification." (PMID 35534881, 2022). "For example, BRCA1 and CRISP2 specific site methylation changes are associated with atherosclerosis, indicating that differentially methylated regions of BRCA1 and CRISP2 emerge as biomarkers for CVD." (PMID 34262910, 2021). "As such, our results show that DNA hypermethylation of most BRCA1 and CRISP2 CpG probes occurs independently of sample variation in blood cell type composition and is associated with atherosclerosis pathology." (PMID 28698603, 2017). "Furthermore, methylation in BRCA1 and CRISP2 DMR was also associated with subclinical atherosclerosis measures in an independent sample of middle age men." (PMID 28698603, 2017). "Altogether, our data suggest that BRCA1 and CRISP2 DNA methylation patterns are potential epigenetic biomarkers related to atherosclerosis in blood and atherosclerotic plaque tissue matrix." (PMID 28698603, 2017). "Data on CRISP2 methylation and its role in atherosclerosis is a novel concept." (PMID 40076974, 2025). "In this study, we identified genomic regions in BRCA1 and CRISP2 which were consistently differentially methylated in blood DNA of atherosclerosis patients compared to healthy individuals, and in aortic and carotid plaque samples compared to aorta samples without plaque." (PMID 28698603, 2017). "Moreover, BRCA1 and CRISP2 target genes demonstrate significant hypermethylation in atherosclerosis blood samples, as compared to blood samples derived from healthy individuals." (PMID 28698603, 2017). "Differentially methylated BRCA1 and CRISP2 regions were verified by MassARRAY Epityper and pyrosequencing assays and could be further replicated in blood, aorta tissue and carotid plaque material of atherosclerosis patients." (PMID 28698603, 2017). "DNA methylation changes of the BRCA1 and CRISP2 DMRs could also be replicated in an Illumina 450 K dataset of paired atherosclerotic plaque and normal aorta samples from 24 middle aged men with subclinical atherosclerosis of the Aragon Workers Health Study (AWHS)." (PMID 28698603, 2017). "Of special note, the differentially methylated regions in BRCA1 and CRISP2 appeared to be largely independent of age and/or immune cell type composition, and both hold promise as valuable atherosclerosis related biomarkers in routine blood analysis." (PMID 28698603, 2017). "However, observed atherosclerosis related DNA hypermethylation trend for most BRCA1 and CRISP2 CpG probes does not follow the expected methylation change in blood samples enriched for granulocyte and reduced CD8+ T immune cell subpopulations." (PMID 28698603, 2017).
Infertility (6 papers, 2019 to 2026). "Accordingly, high miR-27b and miR-27a expression or low CRISP2 protein expression was significantly associated with low sperm motility, abnormal morphology, and infertility in asthenoteratozoospermic men." (PMID 31058050, 2019). "MiR-27a and -27b negatively regulate the expression of the cysteine-rich secretory protein 2 (CRISP2), and downregulation of the CRISP2 protein was significantly associated with low sperm morphology, low progressive motility, and infertility in AZ patients." (PMID 35886074, 2022). "In conclusion, although our samples were limited, our finding suggested that down-and up-regulation of the CRISP2 and SEMG1 respectively was associated with the idiopathic AZS infertile men." (PMID 31058050, 2019). "Moreover, a correlation was found between CRISP2 expression and low sperm progressive motility, abnormal sperm morphology and infertility, suggesting that the lower expression of CRISP2 in these patients could be due to a post-transcriptional regulation process mediated by miR27 b." (PMID 34970552, 2021). "The impaired function of oxidative phosphorylation could be the predominant reason for crossbred bull infertility; and significant downregulation of ZNF706, CRISP2, TNP2, and TNP1 genes indicates that they could serve as potential biomarkers for fertility in crossbred bulls." (PMID 34041237, 2021).
teratozoospermia (4 papers, 2019 to 2024). "Several studies have shown that protein 4.1, SPATA46, CRISP2, Spata6 and other genes play important roles in the process of normal spermatogenesis and have potential as molecular markers for clinical diagnosis of teratozoospermia." (PMID 33819193, 2021).
cervical cancer (2 papers, 2021 to 2022). A primary or metastatic malignant neoplasm involving the cervix. "We found that the expression of Ki67 was increased according to histopathological stage, whereby high expression of KRT17 was specifically found in cervical cancer and low expression of CRISP2 was specifically observed in HSIL." (PMID 33624385, 2021). "In summary, using a gene‐level to protein‐level analysis, our results demonstrate that KRT17 and CRISP2 are specifically expressed in various histological stages of cervical carcinoma." (PMID 33624385, 2021). "Therefore, we proposed that combined analysis of KRT17 and CRISP2 expression to determine different histological stages of cervical cancer, it would be helpful for accurate histological diagnosis." (PMID 33624385, 2021). "During the progression of cervical cancer, from normal cervical tissues to CIN 1, 2 and 3, the gradually down‐regulated genes we confirmed were CRISP3, CRISP2, PPP1R3C, and DSG1." (PMID 33624385, 2021). "Cysteine-rich secretory protein-2 (CRISP2) has been reported to be less expressed in high-grade squamous intraepithelial lesions than in other histological grades, making it a novel biomarker for the detection of cervical cancer." (PMID 36212177, 2022).
prostate carcinoma (2 papers, 2022 to 2023). A carcinoma that arises from epithelial cells of the prostate gland. "One recent study has reported that prostate secretory protein 94 inhibited sterol binding and export of CRISP2 in a calcium-dependent manner, which affected the prostate physiology and progression of prostate cancer." (PMID 37705744, 2023). "Potential implications of the calcium-dependent interaction between PSP94 and CRISP2 on prostate physiology and their potential role in prostate cancer progression are discussed." (PMID 35063506, 2022). "The observation that PSP94 modulates the sterol binding function of CRISP2 in a calcium-dependent manner has potential implications for the role of PSP94 and CRISP2 in prostate physiology and progression of prostate cancer." (PMID 35063506, 2022). "Both CRISP2 and PSP94 are involved in prostate cancer development and spermatogenesis, and lipids play crucial roles in both processes." (PMID 35063506, 2022). "The observation that the expression of both CRISP2 and CRISP3 is increased in prostate cancer, whereas that of PSP94 is decreased, suggests that these two proteins could exert opposing functions during cancer progression." (PMID 35063506, 2022).
squamous intraepithelial lesions (2 papers, 2021 to 2022). "Cysteine‐rich secretory protein‐2 (CRISP2) was less expressed in high‐grade squamous intraepithelial lesions (HSILs) than in other histological grades." (PMID 33624385, 2021).
varicocele (2 papers, 2015 to 2019). A condition characterized by the dilated tortuous veins of the spermatic cord with a marked left-sided predominance. "Proteins expressed uniquely in the unilateral varicocele group were cysteine-rich secretory protein 2 precursor (CRISP2) and arginase-2 (ARG2)." (PMID 25890347, 2015). "Two proteins that were unique to the varicocele group were cysteine-rich secretory protein 2 precursor (CRISP2) and arginase-2, (ARG2)." (PMID 25890347, 2015). "We found that CRISP2, although in low abundance, was uniquely expressed in the unilateral varicocele group." (PMID 25890347, 2015).
breast carcinoma (1 paper, 2024). "Our analysis of CRISP2 gene mutations underscores its critical role in cancer cell viability, particularly in breast cancer (BRCA)." (PMID 39268471, 2024). "In this study, we conducted a comprehensive analysis of CRISP2 expression in relation to various biological processes and clinical traits in breast cancer (BRCA) patients." (PMID 39268471, 2024). "In breast cancer (BRCA), CRISP2 expression was significantly lower in tumor tissues compared to normal tissues, with diagnostic efficacy indicated by a Receiver Operating Characteristic (ROC) curve showing an AUC of 0.706." (PMID 39268471, 2024).
cervical squamous cancer (1 paper, 2021). "The further IHC results suggested that KRT17 was dominantly expressed in the cervical squamous cancer and barely expressed in the normal cervix; while CRISP2 was specifically lowly expressed in HSIL." (PMID 33624385, 2021). "Combined analysis of KRT17, CRISP2 expression at both genetic and protein levels can determine different histological grades of cervical squamous cell carcinoma." (PMID 33624385, 2021).
chronic pancreatitis (1 paper, 2025). A chronic inflammatory process causing damage and fibrosis of the pancreatic parenchyma. "CRISP2 is a member of the cysteine-rich secretory protein family and has been linked to immunomodulation and pathophysiology of chronic pancreatitis." (PMID 40470116, 2025).
disc degeneration (1 paper, 2024). "Dysregulation of CRISP2 expression has been implicated in disc degeneration, highlighting its potential as a biomarker and therapeutic target for IDD." (PMID 39268471, 2024). "The precise mechanisms by which CRISP2 influences disc degeneration remains to be fully elucidated, but it is postulated that CRISP2 may interact with signaling pathways that regulate oxidative stress and inflammation." (PMID 39268471, 2024).
prediabetes (1 paper, 2011). "Finally, the Cox regression analysis was performed for glycaemic progression (NGT at baseline -> IGT/IFG/T2DM by CRISPS2 or CRISP3; and IGT/IFG at baseline -> T2DM by CRISP2 or CRISPS3) which involved both incident prediabetes and incident T2DM case subjects." (PMID 22163043, 2011).
cancer (7 papers, 2013 to 2024). A tumor composed of atypical neoplastic, often pleomorphic cells that invade other tissues. "Survival analysis demonstrated that CRISP2 expression levels were associated with patient survival across various cancer types." (PMID 39268471, 2024). "Our analysis revealed the correlation between CRISP2 expression and immune cell infiltration, with survival analysis indicating that CRISP2 levels were associated with patient outcomes across various cancer types." (PMID 39268471, 2024). "The expression levels of CRISP2 (z-score normalized) were consistently lower in tumor samples (red boxplots) than in normal samples (blue boxplots) across multiple cancer types, with statistical significance indicated by p-values." (PMID 39268471, 2024). "Univariate survival analyses across various cancer types indicated hazard ratios for mutant versus wild-type CRISP2, underscoring the prognostic relevance of CRISP2 expression." (PMID 39268471, 2024). "Visualization of the top 200 cell lines from the DepMap database shows the essentiality scores for CRISP2, highlighting its importance for cell survival in specific cancer types." (PMID 39268471, 2024). "To confirm the significance of KRT17 and CRISP2 during the period of tumor progression, we further analyzed their expression among normal and cancer samples in 6 datasets with larger sample size." (PMID 33624385, 2021). "This study demonstrates that Hesperidin, a natural metabolic compound targeting CRISP2, effectively mimics the protective effects of estrogen on IDD while mitigating cancer risks." (PMID 39268471, 2024). "Cysteine-rich secretory protein 2 (CRISP2) is involved in cell-cell adhesion and is a member of the CAP superfamily of proteins that are thought to be important in immune function and cancer." (PMID 26220546, 2015). "The observation that A1BG modulates the sterol-binding function of CRISP2 has potential implications for the role of A1BG and related immunoglobulin-like domain containing proteins in cancer progression and the toxicity of reptile venoms containing CRISP proteins." (PMID 39433128, 2024). "Our results revealed that CRISP2 can be a characteristic gene specific to BPH, since the AUC values for distinguishing BPH from normal, cancer, and non-BPH all exceeded 0.9, indicating good predicting performance." (PMID 37705744, 2023).
tumor (4 papers, 2020 to 2024). "This study aims to explore a natural metabolic treatment strategy by targeting CRISP2 with the natural compound Hesperidin to mimic the protective effects of estrogen on IDD and reduce the risk of tumor development." (PMID 39268471, 2024). "Specifically, P5 displayed a two-fold decrease in CEACAM-1, while P1 showed a drop in CRISP-2 to undetectable levels following tumor resection." (PMID 33274048, 2020). "The genes with low expression in the tumor group were CRISP3, FAM3D, SCNN1B, CRISP2, RBM20, PHYHIP, C2orf54, SLC5A1, PTCRA, C15orf59, and ANO10." (PMID 35389773, 2022).
cardiovascular disease (3 papers, 2017 to 2020). "CRISP2 is differentially methylated in atherosclerotic patients, suggesting an association with cardiovascular diseases." (PMID 32303053, 2020). "Future prospective studies in larger and distinct cohorts could further enable the validation of BRCA1 and CRISP2 to predict early cardiovascular disease." (PMID 28698603, 2017).
infection (1 paper, 2025). The state of being infected such as from the introduction of a foreign agent such as serum, vaccine, antigenic substance or organism. "CRISP2, although sperm-specific, regulates ion channels and may influence systemic ion homeostasis under infection-induced stress." (PMID 41366310, 2025).
CRISP2 also shares sentences with these, for which no sentence is quoted: Azoospermia (1 paper); dyslipidemia (1); fertility disorders (1); intervertebral disc degeneration (1); kidney cancer (1); men (1); neurodegenerative disease (1); oligospermia (1); type 2 diabetes (1).